CD4 (CD4 molecule)
Diseases named in the same sentence as CD4 in open-access papers (continued):
Sharing a sentence is not in itself a finding about the gene and the disease.
liver fibrosis (continued). "The result of CD4 > 200/ul as a protective factor to against liver fibrosis in this study supports a mechanism of immune activation, but detectable HIV-RNA as a risk factor for liver fibrosis supports a mechanism of a direct effect of HIV infection." (PMID 34924016, 2021). "However, the significantly elevated APRI scores in HCV/HIV-coinfected patients correlated with CD4+CD25+CD127− regulatory T cell counts, thus indicating an association between higher numbers of these cells and APRI-based predictions of hepatic fibrosis." (PMID 34452314, 2021). "Moreover, overexpression of liver‐specific IDO1 diminished numbers of splenic CD11c+MHCII+, CD11c+CD40+ cells and reduced CD3+, CD3+CD4+ T cells infiltration subsequently during BDL-induced hepatic fibrosis." (PMID 33414436, 2021). "Indeed, within HCV patients, hepatic CD4+Foxp3+ T cells are negatively correlated with liver fibrosis, whereas CD4+Foxp3+ Tregs in the blood of chronic HCV patients are less frequent than in healthy controls." (PMID 33869241, 2021). "It was reported that homeostasis of CD4+ T cells is pivotal in liver fibrosis." (PMID 33535174, 2021). "In addition, we saw increased DPP4 (CD26) on CD4+ T cells and NK cells, which concurs with our previous observation that DPP4 gene knockout mouse livers had fewer intrahepatic CD4+ T cells in a liver fibrosis model." (PMID 34771657, 2021). "MiR-29a and miR-652 improve liver fibrosis through inhibiting differentiation of CD4+ T cells." (PMID 34161325, 2021). "Liver fibrosis (measured by both transient elastography and liver biopsy) was statistically significantly associated with intrahepatic mRNA for CXCL10 and CXCR3 using linear and logistic regression analyses adjusted for CD4 T-cell count." (PMID 32898182, 2020). "The higher CD4 and platelet counts may reflect the well-preserved host immune status and the degree of liver fibrosis, respectively." (PMID 32702915, 2020). "The objective of this study was to evaluate hepatic fibrosis in HIV/HCV co-infected participants as compared to HCV mono-infected using APRI score; In addition, we also evaluated the effect of HIV viremia and CD4 count on the occurrence of hepatic fibrosis in HIV/HCV co-infected participants." (PMID 33059627, 2020). "The question remains whether the effect of belatacept on CD4+ T cell response in regard to the reduction of hepatic fibrosis is restorable in case of a CTLA-4-Ig treatment stop." (PMID 31950032, 2019). "To further understand whether Th17 CD4+-T cells are involved in the pathogenesis of hepatic fibrosis, we investigated the role of IL-17A in relation to S. mansoni disease severity." (PMID 29610679, 2018). "Previous study reported that CD8+ T cells could induce more liver injury and fibrosis in mice treated with CCl4, and CD4+/CD8+ ratio reduction also involved in induction of liver fibrosis in human." (PMID 29720975, 2018). "Compared to HIV mono-infected, co-infected patients were older, less likely to be male or of African/Caribbean ethnicity, more likely to have a history of IDU and have liver fibrosis, less likely to be on a tenofovir-based initial cART regimen and had lower baseline CD4+ cell counts." (PMID 28376824, 2017). "Unfortunately we had no clinical outcomes to relate to, but a hospital-based study found that, independent of age, decreased CD4+ memory telomere length was associated with increased liver fibrosis." (PMID 27034702, 2016). "Interestingly, two potentially modifiable factors, CD4+ nadir and serum 25(OH)D levels, were both independent modulators of liver fibrosis progression and determinants of portal pressure." (PMID 26273302, 2015). "Although several studies have focused on the contribution of Th2 cells to chronic inflammatory disease and fibrosis, which is characterized by the cytokines IL-4 and IL-13, CD4+ IL-17-secreting T cells have been shown to contribute to pathology in some models of liver fibrosis." (PMID 25590646, 2015).
liver fibrosis (continued). "In addition, IL-13 acts as a profibrogenic factor involved in a protective mechanism characterized by formation of CD4+ T cell-driven liver granulomas, which leads to liver fibrosis." (PMID 26258681, 2015). "Although there was only a trend toward a higher risk of advanced liver fibrosis in patients with low CD4+ nadir, we would not challenge the relevance of CD4+ nadir as a determinant of liver disease progression." (PMID 26599080, 2015). "CD4 lymphocyte counts showed a tendency to improved liver fibrosis (p=0.056)." (PMID 25394140, 2014). "A decrease of > 20% in CD4+ cell count between the two biopsies (OR 4.88, 95% CI 1.59-15, P = 0.007), and higher ALT values at first biopsy (OR 4.16, 95% CI 1.22-14.1, P = 0.02), were significantly associated with the progression of liver fibrosis." (PMID 22706343, 2011). "This selectivity in blocking effector CD4 T cell recruitment while preserving the presence of immunomodulatory Tregs may have played a crucial role in the effectiveness of α4β7 and MAdCAM-1 mAbs in suppressing hepatic fibrosis." (PMID 38727292, 2024). "In this study, the results of multivariate analysis showed that variables related with HIV natural history (such as levels of HIV RNA and CD4+ T-cell count) and HIV-associated intervention (such as cART) could affect FIB-4 scores and the incidence of liver fibrosis." (PMID 34924016, 2021). "Additionally, the accumulation of ‘exhausted’ CD4 T cells (mt-Co1+) has been found in a terminal stage of liver fibrosis, indicating that CD4 T cells could be a negative regulator in liver injury and fibrosis." (PMID 33391261, 2020). "In HIV infected patients the chronic inflammation due to low CD4/CD8 ratio can possibly lead to chronic inflammation of the hepatocytes causing constant hepatocytes’ death and regeneration, which, in long term, could lead to liver fibrosis." (PMID 32252653, 2020). "Here, we show for the first time that progression of liver fibrosis is associated to a defective NK cell function that could not be attributed to a defective modulation by CD4+ T‐cells." (PMID 31536177, 2019). "A low CD4+ T‐lymphocyte count may contribute to impaired stimulation of natural killer cells, which could result in reduced antifibrotic activity on hepatic stellate cells and consequently progression to liver fibrosis." (PMID 30394678, 2018). "This approach might have missed any association between liver fibrosis and CD4 count as we did not have information on time spent by patients in an immune-compromised state." (PMID 28362065, 2017). "In addition, the up-regulation of cytotoxicity pathway in HH versus HIV as well as in HIV versus HCV has been found in CD4+ T cells, and high percentages of cytotoxic CD8+ T cells associated with liver fibrosis in co-infected patients have been detected by the flow cytometry study." (PMID 25623235, 2015). "In addition to this, HIV-specific markers such as high pre-ART viral load and lower CD4 counts were independently associated with a higher FIB-4 index, suggesting that HIV disease progression may favor the progression of liver fibrosis per se." (PMID 26640953, 2015). "Together, these studies provide a proteogenomic single-cell atlas for hepatic CD4+ T cells and uncover a CD4+ T cell-dependent immunopathogenic circuit as a promising immunotherapeutic target to alleviate MASH and liver fibrosis." (PMID 40631180, 2025). "In the current study, using an established model of CCl4-induced liver fibrosis, we show a critical role of α4β7+ CD4 and α4β7+ CD8 T cells in promoting hepatic fibrosis progression." (PMID 38727292, 2024). "In a study, the depletion of total CD4+T cells reduced the inflammation observed in NASH and ameliorated NAFLD activity scores and liver fibrosis in humanized NASH mice, indicating the functional role of CD4+T cells in NASH development." (PMID 39000005, 2024). "IL17, produced mainly by CD4+ (TH17) and CD8+ (Tc17) T cells, is essential in mediating inflammation and liver fibrosis." (PMID 39459627, 2024).
liver fibrosis (continued). "The abundances of senescent CD4+ and CD8 + T cells and the HOMA-IR positively correlated with the severity of liver fibrosis, assessed using MRI-based elastography." (PMID 37735474, 2023). "CD4+ memory static T cells secrete iconic cytokines IL-4, IL-10, and IFN-G, and stimulate other immune cells such as NK cells, to media the progress of liver fibrosis." (PMID 36686655, 2022). "A recent study explored the role of CD4+T cells in a high-fat diet-induced (HFD) mouse model of humanized NAFLD and found that it has an important role in promoting liver fibrosis." (PMID 35935983, 2022). "CD4+T cells are involved in the pathological process of NAFLD and promote the occurrence of liver fibrosis and even liver cancer." (PMID 35935983, 2022). "By contrast, overexpression of IDO1 significantly aggravated liver fibrosis, accompanied by a dramatically reduced percentage of CD11c+MHCII+, CD11c+CD40+ cells and CD3+, CD3+CD4+ T cells in hepatic NPCs of fibrotic livers." (PMID 33414436, 2021). "In the sixth study, S. mansoni-coinfected persons exhibited less frequent and smaller intrahepatic HCV-specific CD4+ Th1 responses than those with HCV mono-infection, and biopsy-confirmed liver fibrosis was inversely correlated with the Th1 immune response." (PMID 34015063, 2021). "This is the first study showing a comparative immunophenotypic profile of the activation of iNKT cells, CD4+ and CD8+ T cells in PBMC from NAFLD with different degrees of liver fibrosis and DILI patients." (PMID 35052736, 2021). "In summary, these results show that CD4+ T cells play diverse roles in the development of NAFLD, liver fibrosis, and HCC." (PMID 34869507, 2021). "The frequency of CD25+CD45+CD4+ T cells was increased in PBMCs of human NAFLD patients with advanced liver fibrosis, while the PD1+CD4+ T cells were decreased, which were significantly and negatively correlated with the ratio of serum fatty acid composition." (PMID 34869507, 2021). "Most of the 49 patients included in the study were males (79.6%), the median age was 52 years (IQR 51–55 years) with a median CD4 cell count at BL as 550 cells/mm3 (IQR 320–642 cells/mm3) and a diagnosis of advanced liver fibrosis (85.7%)." (PMID 33927306, 2021). "CD4 counts and plasmatic HIV viral load of HIV/HCV co-infected individuals were determined and the correlation between hepatic fibrosis and immuno-virological status established." (PMID 33059627, 2020). "The decrease in CD4 count levels, due to HIV infection, leads to a reduction in the anti-fibrotic activity of NK cells, which leads to rapid progression of hepatic fibrosis in HIV/HCV co-infected individuals." (PMID 33059627, 2020). "We therefore speculated that in C. sinensis-induced liver fibrosis, the modulation of CsTPs-induced DC might be the initiation of the subsequent immunologic cascade as its strong capacity for priming type 2 immune response and CD4+ T cell has a crucial role in orchestrating this immune response." (PMID 29505573, 2018). "The median baseline CD4+ count was 461 cells/mm3, 76.1 % had plasma HIV-RNA <50 copies/mL, 63.3 % had significant liver fibrosis (≥F2), 26.2 % had plasma HCV-RNA <500,000 UI/mL, and 45.8 % had the favorable genotype of IL28B polymorphism (AA rs12980275)." (PMID 27590274, 2016). "Taken together, not only α-GalCer but, importantly, OCH administration induced more inflammatory cells to liver, including activating CD4+ and CD8+ T, NK, and B cells, which led to portal inflammation and liver fibrosis." (PMID 25807531, 2015). "Growing body of evidence have supported accelerated liver fibrosis and organ failure in HIV/HCV co-infected compared to HCV mono-infected individuals especially in those with CD4 T cell count below 200 cells or at advanced stage of the HIV disease." (PMID 25528160, 2014).
liver fibrosis (continued). "Differences in expression of activation and exhaustion markers (HLA-DR, CD38, PD-1, Tim-3 and Fas) and phenotypic markers on CD4+ and CD8+ T-cells were analysed by flow cytometry and were related to HCV disease parameters (HCV-viremia, ALT and liver fibrosis)." (PMID 23555014, 2013). "Another study reported that CD161+CD4+T cells aggregated in the HBV patient's liver and influenced the progression of liver fibrosis through the production of IFN‐γ and IL‐17, whereas the effect that CD8+T cells expressing CD161 in the course of HBV infection is unclear." (PMID 39799583, 2025). "In the liver fibrosis models, non-effector cells like naïve T cells, Tregs, and exhausted T cells progressively differentiated into effector T-cell pathways, including CD4, CD8, and memory T cells." (PMID 40868044, 2025). "In contrast, the heightened glucose metabolism in CD4+ T cells may contribute to developing and progressing NAFLD, liver fibrosis, and autoimmune hepatitis (AIH)." (PMID 40122853, 2025). "Nadir CD4+ T cell percentage <10% was more common in progressors compared to non-progressors, (when liver fibrosis was defined either by 9/11 (82%) versus 15/44 (34%) stage, or 8/9 (89%) versus 16/46 (35%) by kPa)." (PMID 38518655, 2024). "Clinically, 1167 (65%) of the cohort had a suppressed HIV viral load with a median CD4 cell count of 418 cells/mm3; 316 (17%) reported past HCV treatment; 203 (11%) had advanced liver fibrosis, and 91 (5%) had a recent diagnosis of a sexually transmitted infection." (PMID 38798898, 2024). "Overall, CD4+ helper T cells play a role in the pathogenesis of MASH, as demonstrated by the depletion of CD4+ cells in a humanized mouse model of MASH leading to hepatic fibrosis." (PMID 38892602, 2024). "Improvement in liver fibrosis was associated with a significant decrease in the infiltration of α4β7+ CD4 and CD8 T cells, suggesting that α4β7/MAdCAM-1 axis regulates both CD4 and CD8 T cell recruitment to the fibrotic liver, and α4β7+ T cells promote hepatic fibrosis progression." (PMID 38727292, 2024). "The importance of this parameter is evidenced by the data that patients with CHC show reduced CD4+/CD8+ ratios compared to the healthy control group, and patients with F3-F4 liver fibrosis and cirrhosis demonstrate much lower CD4+/CD8+ ratios than patients with F0-F2 fibrosis and fatty liver do." (PMID 37372076, 2023). "The study also underlines the changes in the risk factors for liver fibrosis over time, due to ART, given that at the last visit the CD4 T cell count and non-adherence to ART were still associated with liver fibrosis." (PMID 35966860, 2022). "However, depletion of CD4+T cells in HFD mice not only prevented liver steatosis but also significantly reduced immune infiltration and liver fibrosis." (PMID 35935983, 2022). "Additionally, knock out of IDO1 induced a distinct increase in the frequency of CD3+ T cells, and the ratio of CD4+/CD8+, whereas reduced the frequency of CD8+ T cells in hepatic NPCs under the condition of liver fibrosis." (PMID 33414436, 2021). "Finally, we observed a positive correlation between intrahepatic CCR5+ frequency and liver fibrosis in both monoinfected (CD4: r = 0.69 p = 0.005; CD8: r = 0.65 p = 0.01) and coinfected patients (CD4: r = 0.92 p = 0.0001; CD8: r = 0.85 p = 0.0001)." (PMID 34696504, 2021). "Notably, TcrbKO livers displayed negligible T cell populations (both CD4 T and CD8 T cells) as well as expanded activated macrophages (cluster 7) and γδ T cells (cluster 15) in liver fibrosis." (PMID 33391261, 2020). "This indicated, regardless of CD4 levels, earlier ultrasound screening to find occult liver fibrosis was necessary, especially among HIV/HBV or HIV/HCV co-infected patients." (PMID 33351812, 2020). "CD4+ T cell-depletion did not prevent hepatic steatosis, but decreased liver immune infiltration and liver fibrosis." (PMID 33013934, 2020).
liver fibrosis (continued). "On multivariate logistic regression analysis older patient’s age, abnormal serum aspartate aminotransferase (AST) value, Hepatitis C virus (HCV) infection, alcohol abuse, CD4/CD8 ratio and an increased number of liver related events (LREs) were significantly correlated with liver fibrosis/cirrhosis." (PMID 32252653, 2020). "We aimed to evaluate the levels of peripheral CD4+ T cells (Tregs) and plasma cytokine in patients coinfected with human immunodeficiency virus and hepatitis C virus (HIV/HCV) according to liver fibrosis stages [evaluated as liver stiffness measure (LSM)] and their linear relationship." (PMID 30400258, 2018). "This may be associated with the crucial function that transforming growth factor (TGF)-β1 has in the development of liver fibrosis and the fact that cooperation between TGF-β1 and IL-6 may promote maturation of CD4+ T cells into Th17 cells." (PMID 25323532, 2015). "To account for the progression to liver disease and for advanced HIV disease, in the final multivariate model we included not only the APRI score, which has been shown to be a reliable marker for predicting hepatic fibrosis in HIV/HCV co-infected patients, but also nadir CD4 cell count." (PMID 26537918, 2015). "The most relevant potential mechanisms that lead to a higher CD4 count when HIV subjects are treated for HCV and achieve SVR include the regression of liver fibrosis that may lead to the prevention of splenomegaly and cirrhosis." (PMID 25688301, 2015). "In HIV-1 positive individuals co-infected with S. mansoni, reduced CD4+ T-cells counts levels did not necessarily imply the development of severe hepatic morbidities or altered patterns of hepatic fibrosis due to the effects of hepatotoxins." (PMID 23849678, 2013). "We found that the frequencies of CD4+CD25+ and CD4+IL-17+ cells significantly increased in mouse livers and spleens after ConA administration, suggesting the involvement of Treg and Th17 responses in ConA-induced liver fibrosis." (PMID 22745730, 2012). "From an overall perspective, we demonstrated that total CD4+ cells from CHB patients dramatically promoted cell proliferation, α-SMA expression and growth factors production (TGF-β, PDGF-BB, CTGF and EGF) of HSCs, thus promoting liver fibrosis progression." (PMID 22745730, 2012). "In a recent study by Sim at al., higher levels of CD8+CD28−CD57+ and CD4+CD28−CD57+ cells were observed in the livers of patients with type 2 diabetes and MASH or liver cirrhosis, compared with healthy controls, and correlated with the severity of liver fibrosis." (PMID 38596669, 2024). "In addition to their role in liver fibrosis, it is argued that high levels of CCL2 can severely affect the course of HIV infection by up-regulating HIV-co-receptor CXCR4 on CD4+ T cells and polarization of helper T cells towards Th2 phenotype, a hallmark of progressive HIV disease." (PMID 25528160, 2014). "The altered balance between CD4 and CD8 response in HIV infection may be ascribable to a profound dysregulation of the peripheral and intrahepatic cytokine networks, which plays an important role in the accelerated evolution of liver fibrosis." (PMID 24865485, 2014). "The study demonstrated that hepatic fibrosis, in the absence of severe hepatosplenomegaly, was associated with a significant decrease in CD4+ T-lymphocytes in HIV-1 negative individuals infected with S. mansoni, and that the decrease correlated with increasing grade of liver fibrosis." (PMID 23849678, 2013). "In this study, HIV RNA, and not CD4+ cell count, was the best predictor of liver fibrosis." (PMID 22706343, 2011). "However, exact CD4+ levels for liver fibrosis have not been standardized." (PMID 38787212, 2024). "We observed that, as previously reported, activated CD4+ cells, CD8+ T cells are increased in patients with advanced fibrosis compared to patients without liver fibrosis." (PMID 37392250, 2023).